UEVLD (UEV and lactate/malate dehyrogenase domains)
Description:
Possible negative regulator of polyubiquitination.
Synonyms: UEV3; Attp
Tractability: Small molecule: it has a binding pocket of medium quality. PROTAC: ubiquitination databases record sites on it; its protein half-life has been measured.
Gene: Protein-coding gene on chromosome 11 (18,529,607 to 18,588,747, reverse strand). Ensembl gene ENSG00000151116.
Subcellular location (Human Protein Atlas): Nucleoplasm; Cytosol
Gene Ontology:
Molecular function: protein binding; catalytic activity; oxidoreductase activity; oxidoreductase activity, acting on the CH-OH group of donors, NAD or NADP as acceptor
Biological process: endosome to lysosome transport; protein transport; regulation of DNA-templated transcription
Cellular component: extracellular exosome; ESCRT I complex; cytoplasm; vesicle
Genetic constraint (gnomAD): Loss-of-function variants: 33 observed, 44.71 expected, observed/expected ratio (o/e) 0.74, 90% interval 0.56 to 0.99. The upper end of that interval is the gene's LOEUF score, 0.99, which puts it in group 4 of 6, group 1 being the genes least tolerant of losing a copy. Missense variants: 433 observed, 494.93 expected, observed/expected ratio (o/e) 0.87, 90% interval 0.81 to 0.95. Synonymous variants: 172 observed, 173.71 expected, observed/expected ratio (o/e) 0.99, 90% interval 0.87 to 1.12.
Homologues: Orthologues: chimpanzee UEVLD (99% identical), macaque UEVLD (93% identical), pig UEVLD (93% identical), dog UEVLD (92% identical), rabbit UEVLD (91% identical), guinea pig UEVLD (87% identical), rat Uevld (84% identical), mouse Uevld (84% identical), tropical clawed frog uevld (58% identical), zebrafish uevld (50% identical), Drosophila melanogaster TSG101 (18% identical), Caenorhabditis elegans tsg-101 (15% identical). Paralogues in human: TSG101 (24% identical).
Diseases named in the same sentence as UEVLD in open-access papers:
UEVLD is named in the same sentence as 2 diseases in open-access papers, as found by Europe PMC text mining. Sharing a sentence is not in itself a finding about the gene and the disease. The quoted sentences say what the papers report.
cancer (1 paper, 2025). A tumor composed of atypical neoplastic, often pleomorphic cells that invade other tissues. "Ubiquitin-conjugating enzyme E2 variant (UEV) and lactate/malate dehydrogenase (UEVLD), also known as UEV3, is a human paralogue of Tsg101 with apparent associations to cancer, innate immunity, NF-κB signaling, and autophagy." (PMID 40571836, 2025).
tumor (1 paper, 2023). "Among most of these tumor types, a negative correlation between gene methylation and mRNA expression was revealed by calculating the Spearman correlation, including HIF1A, SLC16A1, UEVLD, SLC16A8, PFKFB2, LDHB, and SLC16A3." (PMID 37122693, 2023).